MMP9 (matrix metallopeptidase 9)
Diseases named in the same sentence as MMP9 in open-access papers (continued):
Sharing a sentence is not in itself a finding about the gene and the disease.
cancer (continued). "In addition, as a H3-K4 methyltransferase, SMYD3 trans-activates many genes, including MMP-9, Bcl-xL, WNT10B, and Nkx2.8, all of which play critical roles in cancer development and/or progression." (PMID 32007952, 2020). "The quantitative Reverse transcription polymerase chain reaction (qRT-PCR) assay revealed that the Messenger RNA (mRNA) of SAA-1 and SAA-4 was much higher in cancer tissues than in adjacent tissues, and MMPs was up-regulation including MMP-1, MMP-9 and MMP- 12 in OVCAR-3 cell stimulated by SAA." (PMID 32517794, 2020). "A qPCR analysis also revealed elevated expression of the cancer stemness-related genes MMP2, MMP9, Nanog and SOX2, suggesting that NPC43 PD_R cells may have acquired an increase in cancer stemness." (PMID 33243298, 2020). "Furthermore, this increased expression of several MMPs, including MMP-9, MMP-2, and MT1-MMP (i.e. MMP-14), are secreted by a variety of metastatic cancer cells to aid in ECM degradation." (PMID 32829709, 2020). "Finally, the positive control, the hydroxamate-based MMP inhibitor NNGH, showed IC50 values of 29–187 mM for antiproliferation activities against various cancer cell lines, and against MMP-2 and MMP-9 showed values of 0.0091 and 0.0088 mM, respectively." (PMID 32967141, 2020). "We found that AIM suppressed NF-κB activation induced by TNF-α in MCF-7 cells, and the upregulation of NF-κB-regulated genes (COX-2; MMP-2, MMP-9, and VEGF) involved in cancer cell proliferation (COX-2, C-myc, Cyclin-D1), and invasion, adhesion, and angiogenesis (MMP-2, MMP-9, ICAM-1, VEGF)." (PMID 32455624, 2020). "Matrix metalloproteinase-9 (MMP-9) plays a crucial role in cell invasion and cancer metastasis." (PMID 32408577, 2020). "However, in many cancer cell lines, the MMP-2 and MMP-9 expression at both transcriptional and translational levels was regulated by PI3-K/AKT signalling pathway." (PMID 33003361, 2020). "In cancer cell line models CD44+ cells demonstrated significantly elevated MMP-2 and MMP-9 levels compared to CD44- cells, further indicating that CD44 is involved in MMP-2 and MMP-9 expression." (PMID 33335857, 2020). "We revealed for the first time that the actinoporin was able to inhibit cancer colony formation and cell migration via suppression of MMP-2 and MMP-9 expression and induce cell apoptosis via activation of caspase-3, cleavage of PARP, activation of Bax and suppression of Blc-2 expressions." (PMID 33348592, 2020). "In addition to the anti-proliferative activity via hTERT down-regulation, chrysin- and curcumin-loaded nanoparticles can suppress metastasis of cancer cells via reducing expressions of MMP-2 and MMP-9." (PMID 32992587, 2020). "MMP-2 and MMP-9 are key molecules in cancer invasion by the proteolytic digestion of the extracellular matrix (ECM) which is the first step to metastasis to help cancer cells to migrate into or out of the vessel walls to metastasize to the distant organs." (PMID 33233701, 2020). "It is possible that the upregulated GRP78 may promote MMP-2, MMP-9 and uPA expression to increase ECM degradation, leading to cancer cell invasion." (PMID 32393740, 2020). "MMP-9 breaks down the physical barrier formed by ECM, promoting cancer metastasis and inflammation." (PMID 33373399, 2020). "Although its role is not clear in cancer, many studies have reported the importance of MMP-9 expression in OSCC." (PMID 33123565, 2020). "At 20 μM, the established compound carboplatin, a platinum-based anticancer drug, also decreased cancer cell viability but did not suppress tumoroid formation and the MMP9 promoter." (PMID 32102440, 2020). "In cancer development, BRD4 was a stimulator for the expression of cell proliferation related genes, such as c-Myc, CyclinD1 and CDK4, as well as cell migration related genes, such as MMP-2 and MMP-9." (PMID 32640974, 2020).
cancer (continued). "Hypoxia stimulates the interaction of vIIIEGFR with the integrin β3 in GBM cells, activating a signalling pathways c-SRC-dependent resulting in the up-regulation of the cancer cell invasion markers, like matrix metalloproteinase-2 (MMP-2) and matrix metalloproteinase-9 (MMP-9)." (PMID 32486205, 2020). "Apart from that, CD44 also plays an important role in MMP-2 and MMP-9 activation through the binding of proteolytically active MMP-2 and MMP-9 isoforms to the membrane and promoting the cleavage of latent TGF-β, which led to invasion and angiogenesis across various cancer models." (PMID 33335857, 2020). "Furthermore, an overexpression of the exosomal protein, matrix metalloproteinase 9 (MMP9), has been reported in both normo- and asthenozoospermic cancer patients, in agreement with previous reports of its increased expression in infertile men." (PMID 32942548, 2020). "In this study, we demonstrated that the metabolite secretions of GG, M3 and YYC-3 suppressed VEGFA expression and secretion, and limited the expression and secretion levels of MMP2 and MMP9; suggesting that the inhibition of VEGF-MMP signalling pathway is suppressing cancer cell metastasis." (PMID 33228670, 2020). "We next tested whether non GBM cancer cells similarly responded to increased osmolality by producing more uPA, MMP-2 and MMP-9." (PMID 32060379, 2020). "By contrast, after transfection of short hairpin RNA shMMP-9 (for a knockdown of MMP-9) into cancer cells, BB aqueous extracts treatment failed to suppress the cancer cell invasiveness." (PMID 32238777, 2020). "Thus, we suggest that surfactin has the anti-cancer effects by directly inhibiting MMP-2 and MMP-9 levels in response to PM." (PMID 32922544, 2020). "High levels of monomeric forms of LCN2, MMP-9, and LCN2-MMP-9 heterodimers are secreted into the extracellular space, and their levels seem to correlate with the aggressive behavior of neoplastic cells in several types of cancer." (PMID 32575507, 2020). "MMP9 expression has been observed in invasive mammary carcinomas, but not in carcinomas in situ or hyperplastic mammary glands." (PMID 32708426, 2020). "Hereby, inhibition of cancer cell-intrinsic production and secretion of MMP-9, of course, cannot be ruled out." (PMID 31919471, 2020). "Furthermore, MMP-9 is involved in the cleavage of CD25, which is expressed on T cells upon encountering cancer cells." (PMID 32308765, 2020). "Recently, carboxylate-based bivalent inhibitors more specific for MMP-9 were developed, with the aim to disrupt non-covalent MMP-9 dimerization and reduce cancer cell invasion which occurs through the MMP-9 hemopexin domain." (PMID 32645949, 2020). "These molecules could indeed attract cancer cells to intrapancreatic nerves, upregulate MMP–2 and MMP–9 expression along the axons to facilitate extracellular matrix breakdown and cancer progression." (PMID 31248001, 2019). "Cyclosaplin also demonstrated effective binding affinities towards other cancer-related proteins, such as EGFR (−6.8 kcal/mol), VEGFR2 (−7.8 kcal/mol), PKB (−8.1 kcal/mol), p38 (−8.3 kcal/mol), PTEN-tumor suppressor (−6.3 kcal/mol), and MMP-9 (−7.3 kcal/mol)." (PMID 31731771, 2019). "Cancer cell invasion is mediated by breakdown of the basement membrane, a process dependent on extracellular matrix degradation by the matrix metalloproteinase (MMP) enzymes MMP-2 and MMP-9." (PMID 31588240, 2019). "Furthermore, pectolinarigenin markedly impaired cancer cell migration and invasion by down-regulating phosphorylated-Stat3, and expression of matrix metalloproteinase (MMP)-2, MMP-9, while up-regulating the expression of TIMP2." (PMID 31649548, 2019). "MMP9 and MMP2 are common indicators of cancer migration and invasion." (PMID 31346317, 2019). "Therefore, the effect of PRFR on TNF-α-induced proteins was examined that are involved in cancer cell invasion including MT1-MMP, uPA, uPAR, Cox-2, and MMP-9." (PMID 31540489, 2019).
cancer (continued). "MMP9, also known as type IV collagenase or gelatinize B, is a Zn2+ endopeptidase that degrades extracellular matrix (ECM) proteins such as gelatin and collagen resulting in cancer metastasis and invasion." (PMID 31284679, 2019). "If MMP-2 and MMP-9 participate in leptin-dependent migration via FAK activation, their secretion must be controlled by a similar signaling pathway that controls migration of cancer cells." (PMID 31671408, 2019). "In addition, the invasion and aggressiveness of cancer cell lines was significantly decreased by CM-MSC; this was translated by a decrease in MMP-2, MMP-9, and CA-125 mRNA expression, and an increase in TIMP 1, 2, and 3 mRNA expression." (PMID 31351482, 2019). "A panel of MMPs was analyzed in serum from PC patients—specifically, MMP-1, MMP-3, MMP-7, MMP-9, MMP-10, and MMP-12 were higher in cancer patients compared with healthy donors, showing good diagnostic accuracy, of which MMP-7 and MMP-12 achieved perfect discrimination." (PMID 30678058, 2019). "FN1 can induce abnormal expression of some MMPs, such as MMP9/MMP2 and promote proliferation, migration, and invasion in thyroid and gastric cancers." (PMID 30886783, 2019). "MT-MMP, MMP3, MMP9, and matrilysin (MMP7) localize to adherens junctions to shed the E-cadherin ectodomain, producing a soluble fragment frequently increased in the serum of cancer patients." (PMID 31380370, 2019). "SP100, TGFB3 and MMP9 each map to different chromosomes (HSA 2, 14 and 20, respectively) and therefore represent independent repositioning events within the subgroups of different Gleason score cancers." (PMID 31681438, 2019). "Notably, our study showed that MMP1 was targeted by adenine and oxymatrine, and previous evidence has indicated that oxymatrine inhibits the proliferation and facilitates apoptosis of cancer cells through downregulating MMP2 and MMP9 expression." (PMID 31275410, 2019). "In addition, NBP treatment inhibited the matrix metallopeptidase 9 (MMP9) enzyme, which is involved in the degradation of the extracellular matrix during cancer cell migration." (PMID 31049127, 2019). "In conclusion, these data suggest that the coexpression of CXCL8 and MMP9 could be an early detection marker for PNI, with a potential to be utilized as individual therapy targets for early treatment to prevent PNI-related cancer metastasis." (PMID 31681401, 2019). "While most of the studies thus far focus on cancer cells-derived MMPs, emerging evidence indicate that MMPs (including MMP-2 and MMP-9) can also be secreted by the surrounding stromal cells, such as endothelial cells, fibroblasts, myofibroblasts and inflammatory cells." (PMID 29795331, 2018). "Besides COL1A1, serpin family E member 1 (SERPINE1), matrix metallopeptidase 9 (MMP-9) and matrix metallopeptidase 14 (MMP-14), were all drastically increased in cancer lesions as well." (PMID 29720137, 2018). "Indeed, neutrophil-derived MMP-9 induces the release of VEGF from the ECM, and neutrophils have been identified as the major source of MMP-9 in different types of human cancer." (PMID 29953504, 2018). "Our previous reports also have established that a number of matrix metalloproteinases (MMPs), known to be upregulated in cancers, including OSCC, bind and interact with specific MMPs in biochemical and biologic systems: MMP2 with BSP; MMP3 with OPN; MMP9 with DMP1; and MMP20 with DSPP." (PMID 30002682, 2018). "We found that andrographolide exhibited anti-migration and anti-invasive ability against cancer metastasis via inhibition of MMP2 activity rather than affected MMP-9 and EMT." (PMID 30359388, 2018). "IL-20 induces the expression of MMP9, MMP-12, RANKL, cathepsin K and cathepsin G in cancer cells." (PMID 29690863, 2018).
cancer (continued). "MMP2 and MMP9 are members of the matrix metalloproteinase (MMP) family of proteolytic enzymes, and a previous study reported that MMPs are considerably elevated in malignant tumors." (PMID 29805736, 2018). "EGCG has been found to affect several cancer-related proteins including Cyclin-dependent kinase inhibitor p27 (p27), Bcl-2 or Bcr-Abl oncoproteins, Bax, matrix metalloproteinases (MMP-2 and MMP-9) the androgen receptor, EGF receptor, Activator proteins 1(AP1), and some cell cycle regulators." (PMID 30701033, 2018). "Several studies demonstrated a cross-talk between IL-17A and MMP-9, making these two proteins ideal for dual-inhibition, non-antibody cancer therapy." (PMID 29983876, 2018). "Because it is known that MMPs play a major role in promoting metastasis of cancer cells, we first examined the proteolytic activity and expression level of MMP-2 and MMP-9 in ISLA-treated and untreated HT1080 CM." (PMID 30618749, 2018). "However, it appears that MMPs are important enzymes involved in local attack and metastatic PTC cancer, being reported in several studies related to different members of the MMP family, including MMP-1, MMP-2, MMP-7, MMP-9, MMP-10, MMP-13, MMP-14 and MMP-15." (PMID 30509240, 2018). "Because the inhibition of cathepsin expression or activity by a specific siRNA or inhibitor, respectively, did not completely block MDA-MB-231 cancer cell invasion, the role of MMP-9 in synergistic action with CTSB or CTSS was examined." (PMID 30185799, 2018). "Curcumin is a good example of decreasing cancer metastasis in mice by suppressing NF-κB expression and down-regulating VEGF (vascular endothelial growth factor), COX-2, and MMP-9 (matrix metallopeptidase-9) expression in tissues of the breast, brain, lung, liver, and spleen." (PMID 30400131, 2018). "Interestingly, among six cancer cell lines, only EJ-1 and MDA-MB-231 cells exhibited upregulation of NOX4 and MMP9 expression after shRNA-mediated HIC-5 knockdown." (PMID 30281903, 2018). "Thus, considering the earned results, it seems that inhibition of angiogenesis through down-regulation of MMP-2, MMP-9, and VEGF in HNSCC is one the possible mechanisms of cancer treatment." (PMID 30233776, 2018). "Downregulation of KISS1 blocked TGFβ-mediated cancer cell invasion as well as MMP-9 expression and activity in TNBC cells, but not ERα-positive breast cancer cells." (PMID 30123188, 2018). "In addition, ISLA reduced the levels of pro-angiogenic factors such as MMP-9, PlGF, and VEGF in HT1080 CM via suppression of the HIF-1α/Akt/mTOR pathway, supporting the anti-angiogenic activity of ISLA in cancer cells." (PMID 30618749, 2018). "In addition, high expression levels of TGFβ and MMPs at the aggregation point of the NIH3T3 cells and collagen matrix showed that TME-resident fibroblasts affected cancer cells via the storage of MMP1 and MMP9 in the ECM." (PMID 29403007, 2018). "Our results offer additional confirmation to our speculation that MDM2 can shift the balance of the intracellular events in cancer cells towards pro-angiogenic mechanisms through up-regulation of TNF-α, MMP9, and CXCL10." (PMID 29748481, 2018). "The association between high co-expression and co-localization of MMP-9/CD163/CD68 and poor survival in ER+ cancers suggests that these cancers may be candidates for macrophage-targeted therapies." (PMID 30558648, 2018). "Furthermore, AREG affected downstream molecules like BIRC5, CCNA2, CCNB2, TOP2A, MMP9, MMP1, CXCR4, have roles in development and progression of various types of cancers." (PMID 30517191, 2018). "This lacuna in our knowledge prompted us to investigate the molecular mechanisms that could lead to cancer progression during glucose starvation, especially those connected to the activation of LKB1-AMPK-mediated MMP-9 induction." (PMID 29973599, 2018). "In ovine adenocarcinomas, VEGFR2 and VEGFD mRNA were downregulated in cancers; MMP9, TIMP1 and FGFR2 mRNA were overexpressed as compared to normal lungs." (PMID 29137669, 2017).
cancer (continued). "Furthermore, several studies reported that OPN enhanced the migration and invasion of cancer cells by up-regulating MMP-2 and MMP-9 activities via NF-κB pathway." (PMID 29228698, 2017). "Matrix metalloproteinases (MMPs) such as MMP-2 and MMP-9 play critical roles in the proteolytic degradation of the extracellular matrix (ECM) surrounding the primary tumor, which is required for the migration and invasion of cancer cells." (PMID 28481901, 2017). "Another report showed that CXCR1 could up-regulate matrix metalloproteinase-9 (MMP-9) expression by activating JNK/c-Jun and ERK/Ets-1 pathways, thus resulting in more aggressive biological characteristics of cancer cells." (PMID 27780937, 2017). "In our study, MMP2 (and MMP9 for LNCaP) were produced by cell tumors in inactive forms and Apixaban did not activate the MMPs produced by cancer cells." (PMID 29023465, 2017). "Most genes from the “Pathways in cancer” (FLT3, IGF1R, DAPK2, PLD1 and MMP9) are inhibited due to the action of BE resulting in an anti-proliferative and pro-apoptotic action of the combined therapy, with the notable exception of the up-regulation of the apoptosis inhibitor BIRC3." (PMID 28359318, 2017). "Moreover, previous studies also reported that the PI3K-AKT pathway can participate in the invasion and metastasis of cancer cells through increasing expression levels of gelatinases (MMP-2 and MMP-9)." (PMID 28945763, 2017). "In addition, FAK activation further leads to secretion of MMPs such as MMP-2 and MMP-9, which are involved in the degradation of ECM to facilitate cancer cell metastasis." (PMID 28915654, 2017). "Cancer cells secrete MMPs such as MMP2 and MMP9 to promote invasion into surrounding tissues." (PMID 27974675, 2017). "In the present study, MMP9 and FN1, key proteins in cancer pathways, were also upregulated." (PMID 28191466, 2017). "MMP-9 has also been connected to heart disease, tissue damage and cancer metastasis making it a non-specific marker, which is not appropriate to use as diagnostic marker for DMD." (PMID 29263366, 2017). "To determine whether MMPs play an important role in STS-mediated cancer cell invasion, we investigated the expression of MMP-1, MMP-2, and MMP-9 mRNA in PC-3 or HeLa cells expressing STS after exposure to STX-64." (PMID 28977889, 2017). "In our study, we have also found that the BBM-NPs can effectively inhibit migration and invasion which might be due to reduced MMP-2/MMP-9 activation and VEGF expression in highly metastatic cancer cells in comparison to native BBM." (PMID 28724926, 2017). "Some cancer cell lines express both MMP-2 and MMP-9, whereas some cells express only MMP-2." (PMID 28606135, 2017). "TNF-α could induce Twist1 expression and overexpression of Twist1 could promote further metastasis, which increased the expression of MMP-9, MMP-2, CD44v6 and vimentin in cancer cells." (PMID 28774312, 2017). "BITC, PEITC, and SFN suppressed both MMP-9 activity and migration of cancer cells regardless of MMP-2 activity status." (PMID 28969043, 2017). "When CM was analyzed by gelatin and plasminogen zymography, reduced levels of 72/92 kDa (MMP2/MMP9) and 70/45kDa (tPA/uPA) zone clearing activity were detected from daurinol treated MDA-MB-231 and A549 cancer cells compared to the control in a concentration-dependent manner." (PMID 28915654, 2017). "Therefore, we first confirmed the inhibitory effects of PEITC on MMP-9 and MMP-2 in various cancer cells." (PMID 28969043, 2017). "In turn, the increased expression of MMP-9 and MMP-2 leads to a positive feedback loop that might further promote cancer development." (PMID 28869579, 2017). "Cancer cells secrete MMPs (eg, MMP-2 and MMP-9) to degrade the extracellular matrices." (PMID 28938623, 2017).